AQP5 (aquaporin 5)
Diseases named in the same sentence as AQP5 in open-access papers (continued):
Sharing a sentence is not in itself a finding about the gene and the disease.
endometriosis (5 papers, 2015 to 2023). The growth of functional endometrial tissue in anatomic sites outside the uterine body. "Elucidation of the molecular mechanisms associated with AQP5-mediated, migration of endometrial cells may contribute to a better understanding of endometriosis." (PMID 26679484, 2015). "Several AQP isoforms were found related to the etiology of endometriosis; in particular, AQP5 was dose-dependently regulated by estrogens and able to activate the PI3K/AKT pathway, promoting implants of ectopic cells in vivo murine models." (PMID 32046116, 2020). "In the same way, AQP5, whose expression is menstrual cycle-dependent, is more highly expressed in eutopic as compared with ectopic endometrial cells in women with endometriosis." (PMID 33321760, 2020). "AQP5 facilitated glandular epithelium cell migration and invasion in an endometriosis model in mice." (PMID 26679484, 2015). "Our previous studies demonstrated that AQP5 is expressed in in-situ and ectopic, endometrial glandular cells in endometriosis." (PMID 26679484, 2015). "In a previous study, we demonstrated that the expression of ectopic, endometrial AQP5 in patients with endometriosis is menstrual cycle-dependent, and, that AQP5 plays a role in endometrial cancer cell migration." (PMID 26679484, 2015). "AQP5-enhanced invasion and proliferation of ES cells provides further evidence of the involvement of AQP5 in the development of endometriosis." (PMID 26679484, 2015). "We observed that AQP5 promoted the invasion and proliferation of epithelial cells in an endometriosis model." (PMID 26679484, 2015). "Overall, these data suggest the inhibition of Aqp5 expression and AQP5 function may provide new therapeutic options for treating endometriosis." (PMID 36768212, 2023). "AQP5 is also present in physiological tissues, as well as in endometriosis." (PMID 33271827, 2020). "Knockout of AQP5 expression and/or function may be a useful potential therapy to reduce the development of endometriosis." (PMID 26679484, 2015). "Given the common features of cancer and endometriosis, these compounds could induce changes in the ERE of the AQP5 gene, thus regulating its expression." (PMID 33321760, 2020).
Hyperhidrosis (5 papers, 2016 to 2025). Abnormal excessive perspiration (sweating) despite the lack of appropriate stimuli like hot and humid weather. "Polydatin alleviates hyperhidrosis by targeting AQP5 and suppressing key neurologic factors, supporting its potential as a novel therapeutic approach for PFH." (PMID 40880648, 2025). "In conclusion, this study demonstrates that Polydatin alleviates hyperhidrosis symptoms in a mouse model by downregulating AQP5 and NKCC1 expression in sweat glands and reducing neurogenic factors such as BDNF and NRG-1 in sympathetic ganglia." (PMID 40880648, 2025). "AQP5 was proven important in sweat production, possibly responsible for hyperhidrosis in patients with PPKB." (PMID 36232935, 2022). "PAI1 regulation could alter the relative expression of CACNA1C and AQP5, which are vital components involved in the process of sweat secretion and pathological hyperhidrosis." (PMID 37542348, 2023). "PAI1 inhibition with PAI-039 or Pai1 deficiency could induce up-regulated CHRNA1, ACH, AQP5, and CACNA1C expression and sweat secretion in hydrochloride-induced hyperhidrosis mice." (PMID 37542348, 2023). "This suggests that Polydatin may improve hyperhidrosis through the Aqp5 pathway." (PMID 40880648, 2025). "Pai1-Tg mice demonstrated down-regulated secretion of ACH in the serum and down-regulated mRNA and protein levels of AQP5 (and 6 F) and CACNA1C in sweat glands of hydrochloride-induced hyperhidrosis when compared with normal mice exposure to hydrochloride." (PMID 37542348, 2023). "PAI1 inhibits CHRNA1-mediated hydrochloride-induced hyperhidrosis, with decreased sweat gland secretion and diminished ACH, AQP5, and CACNA1C expression." (PMID 37542348, 2023). "The co-expression of AQP5 and TRPV4 in the sweat glands suggested that the interaction might play a considerable role in the pathogenesis of hyperkeratosis and hyperhidrosis." (PMID 36232935, 2022).
injury (5 papers, 2013 to 2025). Damage inflicted on the body as the direct or indirect result of an external force, with or without disruption of structural continuity. "Lipopolysaccharide-induced acute lung injury significantly impaired alveolar fluid clearance; however, following administration of dopamine, this symptom was relieved (via upregulation of AQP1 and AQP5 expression), which may have further promoted the reabsorption of alveolar fluids." (PMID 25009607, 2014). "AQP5, but not AQP1, showed suppressed expression in smothering compared with expression in strangulation and sudden cardiac death and death from acute brain injury." (PMID 34977094, 2021).
Palmoplantar keratoderma (5 papers, 2016 to 2025). Abnormal thickening of the skin of the palms of the hands and the soles of the feet. "Mutations in the AQP5 gene are described as a cause of palmoplantar keratoderma, Bothnian type (OMIM # 600231)." (PMID 36076978, 2022). "There is one described variant in the same codon of the AQP5 gene: c.104G>C (p.(Trp35Ser)) in a patient with keratoderma." (PMID 36076978, 2022). "However, in the PPK2 family with the AQP5 (NM_001651.4): c.103T>G (p.(Trp35Gly)) variant, all affected members from three generations had a more severe skin lesion in mutilating keratoderma, the stratum corneum was swollen and had a white spongy appearance." (PMID 36076978, 2022). "These diseases include cataract (AQP0), autosomal recessive nephrogenic diabetes insipidus (AQP1 and AQP2) and palmoplantar keratoderma (AQP5) and diminished glycerol release (AQP7)." (PMID 36913438, 2023).
viral infection (5 papers, 2005 to 2024). "While other studies have reported decreased levels of AQP5 and associated elevation in lung edema in other viral infections, we found elevated levels of AQPs 4, 5, and 8 in MHV-1 inoculated mice." (PMID 35712703, 2022). "Downregulation of AQP5 in lung injury/edema is caused by various insults such as thoracic irradiation, viral infection and endotoxin, suggesting an important role of AQP5 under these conditions." (PMID 28963443, 2019). "Additionally, AQP5 has been found to be associated with viral infections." (PMID 38380102, 2024). "Viral infection and LPS decrease the AQP5 levels, whereas bleomycin inhalation and thoracic irradiation lead to the increased expression of AQP5." (PMID 27835672, 2016).
acute kidney injury (4 papers, 2018 to 2023). Sudden and sustained deterioration of the kidney function characterized by decreased glomerular filtration rate, increased serum creatinine or oliguria. "In pneumonia evoked ARDS, the AA genotype of the AQP5 -1364A/C promoter SNP is associated with a decreased recovery rate from acute kidney injury and this is independent from the patients net fluid balance." (PMID 30517197, 2018). "Furthermore, we recently demonstrated an association between the AQP5 -1364A/C SNP and susceptibility for acute kidney injury in patients suffering from ARDS." (PMID 32272738, 2020). "In addition, the AA-genotypes of the AQP5 -1364A/C associated with greater AQP5 expression showed increased pulmonary inflammation and an increased risk of acute kidney injury in ARDS13,15." (PMID 31811204, 2019). "Accordingly, we tested the hypothesis that the AQP5 -1364A/C promoter polymorphism is associated with the duration and recovery of an acute kidney injury in patients with ARDS." (PMID 30517197, 2018). "Thus, the functionally relevant AQP5 -1364A/C promoter single nucleotide polymorphism could impact on the development and resolution of acute kidney injury (AKI)." (PMID 30517197, 2018). "The same investigators demonstrated that in ARDS patients suffering from acute kidney injury (AKI), AQP5 1364 A/C was associated with the patients’ recovery rate." (PMID 38203657, 2023).
autoimmune disease (4 papers, 2019 to 2025). A disorder resulting from loss of function or tissue destruction of an organ or multiple organs, arising from humoral or cellular immune responses of the individual to their own tissue constituents. "Although there is a possibility that secondary SS patients without SICCA symptoms were included in the SLE and RA groups, the anti-AQP5 autoantibodies seem to be more prevalent in SS than in other autoimmune diseases." (PMID 31684196, 2019).
cystic fibrosis (4 papers, 2015 to 2025). Autosomal recessive disorder caused by pathogenic variants in the CFTR gene (cystic fibrosis transmembrane conductance regulator), which encodes a chloride and bicarbonate channel expressed in epithelial cells, and follow the diagnosis criteria. "Due to its importance for fluid secretion in airways submucosal glands, AQP5 has been suggested to be a pharmacological target to treat the hyper-viscous and excessive gland secretions in cystic fibrosis and bronchitis/rhinitis, respectively." (PMID 26569106, 2015). "However, the participation of AQP5 in the pathogenesis of celiac disease and cystic fibrosis requires further investigation." (PMID 37681902, 2023). "Celiac disease and cystic fibrosis have been characterized by decreased AQP5 expression in Brunner’s glands which may contribute to the altered duodenal secretion occurring in these diseases." (PMID 37681902, 2023). "Thus, modulation of AQP5 could be a therapeutic strategy to treat disorders of glandular secretion, including both hyper-viscous states such as those observed in Cystic Fibrosis, or excessive glandular secretion characteristic of allergic bronchitis." (PMID 35145418, 2022).
edema (4 papers, 2019 to 2024). An abnormal accumulation of fluid beneath the skin, or in one or more cavities of the body. "Among these, AQP1 and AQP5 are the most important pulmonary aquaporins, and their overexpression is proven to be associated with interstitial edema in severe hypothermia." (PMID 38611652, 2024). "In lipopolysaccharide-induced rat lung damage of disseminated intravascular coagulation, miR-96 and miR-330 targeted Aqp5 mRNA, and concomitantly decreased Aqp5 expression was linked to pulmonary edema." (PMID 36768212, 2023). "Our study suggests that fasudil attenuated LPS-induced pulmonary edema via upregulating the expression of AQP5 and TJ protein occludin." (PMID 28963443, 2019).
ovarian tumor (4 papers, 2010 to 2018). "Similar to AQP9, AQP5 expression was reported to be higher in ovarian tumors associated with lymph node metastasis." (PMID 25344048, 2014). "In summary, our data have revealed a differential distribution of AQP5-ir cells in the ovarian tumor tissue compared with normal ovary suggestive of a potential role of AQP5 in proliferation and invasiveness of ovarian tumor cells." (PMID 25344048, 2014). "Similar to the chicken ovarian tumor, AQP5 localization has also been demonstrated in human ovarian tumor with localization of AQP5 protein in basolateral membrane of epithelial layer in benign tumor and plasma membranes of borderline and malignant tumors." (PMID 25344048, 2014). "Future studies should focus on exploring the pathways involved in altered AQP5 expression and its potential role in tumorigenesis in the chicken model of ovarian tumor." (PMID 25344048, 2014). "AQP5 is differentially expressed in ovarian tumor and in COVCAR cell lines suggesting a potential involvement of AQP5 in ovarian tumorigenesis, metastasis, and survival of ovarian tumor cells in ascites." (PMID 25344048, 2014). "Flattened cells lining the cystic spaces in ovarian tumor were found to be strongly immunoreactive to AQP5 (2 F)." (PMID 25344048, 2014). "Collectively, our data suggest that altered expression of AQP5 may influence ovarian tumor cell proliferation, migration, and survival in ascites." (PMID 25344048, 2014). "The objective of this study was to determine cellular localization of AQP5 in normal and cancerous chicken ovaries and to determine if AQP5 mRNA and protein quantities are different in chicken ovarian tumors and in COVCAR cells compared to that in normal ovaries and NOSE cells, respectively." (PMID 25344048, 2014). "This is the first report to describe AQP5 expression in the chicken ovarian tumor model." (PMID 25344048, 2014). "We hypothesized that AQP5 expression is altered in COVCAR cells and in cancerous ovaries obtained from highly metastatic ovarian tumors compared to normal ovarian surface epithelial (NOSE) cells and normal ovaries, respectively." (PMID 25344048, 2014).
pancreatic adenocarcinoma (4 papers, 2019 to 2024). "It is worth mentioning that AQP5 was found to be overexpressed in pancreatic adenocarcinoma biopsies of patients compared with matched normal pancreas tissues, being correlated with tumor stage and aggressiveness." (PMID 31277235, 2019). "Here, we report that human AQP5 facilitates H2O2 uptake in hAQP5-transformed yeast cells, an ability also detected in a cultured pancreatic adenocarcinoma cell line." (PMID 31277235, 2019).
pancreatic ductal adenocarcinoma (4 papers, 2022 to 2025). An infiltrating adenocarcinoma that arises from the epithelial cells of the pancreas. "Previously, we showed that AQP5 increases in the early stages of pancreatic ductal adenocarcinoma and decreases in the late stages, which correlates with the observations that we report in the present study." (PMID 40305202, 2025). "AQP3 and AQP5 are overexpressed in pancreatic ductal adenocarcinoma, playing key roles in cell migration, proliferation, and invasion." (PMID 35455986, 2022). "Interestingly, AQP3-, AQP5- and double-silenced human pancreatic ductal adenocarcinoma cells exhibited morphological alterations and reduced cell–cell adhesion, with AQP5 additionally affecting cell stiffness and membrane fluidity." (PMID 39941100, 2025). "Interestingly, AQP3 and AQP5 expression patterns vary during the progression of pancreatic ductal adenocarcinoma." (PMID 39941100, 2025). "AQP3 and AQP5 were shown to mediate H2O2 transport in pancreatic ductal adenocarcinoma BxPC3 cells." (PMID 39125952, 2024). "In a previous study, AQP3 and AQP5 expression was investigated in pancreatic ductal adenocarcinoma (PDA) human biopsies by immunohistochemistry and, although both AQPs have peroxiporin activity, their expression pattern was different during the development of the tumor." (PMID 35455986, 2022). "In pancreatic ductal adenocarcinoma cells BxPC3, AQP3 and AQP5 facilitate H2O2 influx, and silencing these homologs results in impaired cell migration." (PMID 39125952, 2024).
Polyuria (4 papers, 2013 to 2020). An increased rate of urine production. "In either case, upregulation of Aqp5 may contribute to the polyuria phenotype in Dot1lAC mice and in DN patients." (PMID 23326416, 2013). "In this report, we uncover a new mechanism by which Dot1l regulates water homeostasis, and identify Aqp5 as a potential novel target of Dot1a, a binding partner of Aqp2, a negative trafficking regulator of Aqp2, and thus the potential missing component linking disrupted Dot1l to polyuria." (PMID 23326416, 2013). "The study suggests that up-regulated AQP5, perhaps by reducing AQP2 membrane localization, may contribute to polyuria." (PMID 27455244, 2016).
triple-negative breast carcinoma (4 papers, 2021 to 2025). An invasive breast carcinoma which is negative for expression of estrogen receptor (ER), progesterone receptor (PR), and human epidermal growth factor receptor 2 (HER2). "High protein expression of AQP1, AQP3 (triple-negative breast cancer) and AQP5 (early and triple-negative breast cancer) revealed a correlation with spread to lymph nodes and poor prognosis." (PMID 37681917, 2023). "In triple-negative breast cancer (TNBC) patients, markedly higher expression of AQP5 and AQP3 was observed in cancer tissue than in adjacent normal tissue." (PMID 33947079, 2021).
acute lung injury (3 papers, 2022 to 2025). A condition of lung damage that is characterized by bilateral pulmonary infiltrates (pulmonary edema) rich in neutrophils, and in the absence of clinical heart failure. "In conclusion, the regulation and expression of aquaporins, particularly AQP1 and AQP5, play a critical role in fluid transport and inflammatory responses in acute lung injury (ALI)." (PMID 39544938, 2024). "Niclosamide was found to upregulate AQP5 expression, which could be beneficial in pathologies with reduced AQP5 levels such as acute lung injury, while methazolamide was reported to reduce AQP5 expression, with an impact on the migration of immune cells." (PMID 39941100, 2025).
bacterial pneumonia (3 papers, 2019 to 2024). Acute infection of the lung parenchyma caused by bacteria (e.g., Streptococcus pneumoniae, Haemophilus influenzae, Chlamydia pneumoniae, Mycoplasma pneumoniae, and Legionella pneumophila). "Therefore, GOL can effectively promote the expression of AQP5 before bacterial pneumonia causes lung injury." (PMID 35518345, 2022).
chronic obstructive pulmonary disease (3 papers, 2010 to 2022). A chronic and progressive lung disorder characterized by the loss of elasticity of the bronchial tree and the air sacs, destruction of the air sacs wall, thickening of the bronchial wall, and mucous accumulation in the bronchial tree. "In chronic obstructive pulmonary disease, AQP5 expression is associated with the progression of COPD, and affects lung function." (PMID 35068345, 2022). "Genetic variants in the AQP5 gene might be associated with rate of lung function decline in chronic obstructive pulmonary disease (COPD)." (PMID 21151978, 2010). "Whereas decreased AQP5 expression and overproduction of MUC5AC have been reported in airways of patients with chronic obstructive pulmonary disease (COPD)." (PMID 29112967, 2017).
dental caries (3 papers, 2017 to 2022). The decay of a tooth, in which it becomes softened, discolored, and/or porous. "The rs1996315 marker is located between AQP5 and 6 and is a substitution of G for A, being reported as associated with dental caries." (PMID 32130259, 2020). "However, the best evidence for AQP5 on dental caries susceptibility suggests a role during dental enamel formation." (PMID 32130259, 2020). "AQP5 interactions during dental development may impact the formation of dental enamel and susceptibility to dental caries." (PMID 28275354, 2017). "Our data confirm the association between dental caries and genetic variation in BTF3 and AQP5 we have previously reported." (PMID 28275354, 2017).
emphysema (3 papers, 2014 to 2022). "In models of COPD, AQP5 knock-out mice are protected from cigarette smoke-induced emphysema, in a mechanisms hypothesized to be related to altered epithelial barrier function and reduced neutrophil recruitment to the lung." (PMID 35145418, 2022). "In this regard, it has been recently shown that AQP5 may regulate cigarette smoke-induced emphysema by modulating the barrier and immune properties of the epithelium." (PMID 24917931, 2014). "Enhanced lung edema formation triggered by I/R probably may be due to downregulation of aquaporin-5 (AQP-5) channels in ATI cells, reduced surfactant protein-C (SP-C) production in ATII cells, and/or emphysema-like changes in the overall lung architecture." (PMID 32931478, 2020).
endometrial cancer (3 papers, 2015 to 2022). Primary or metastatic malignant neoplasm involving the endometrium (mucous membrane that lines the endometrial cavity). "Downregulation of aquaporin-5 (AQP5) showed a reduction in endometrial cancer cells’ migration capacity." (PMID 36230654, 2022). "Increased transcript levels for AQP5 were correlated with poor survival, with hazard ratios of 1.4 in endometrial cancers." (PMID 32679804, 2020).